INS (insulin)
Diseases named in the same sentence as INS in open-access papers (continued):
Sharing a sentence is not in itself a finding about the gene and the disease.
Hyperglycemia (continued). "Historically, hyperglycemia has been managed by a sliding scale insulin regimen, which entails bolus administration of short-acting insulin only." (PMID 38919469, 2024). "EIAS is characterized by hyperinsulinemia, positive insulin antibodies, hyperglycemia, hypoglycemia, or alternation between the two after the administration of exogenous insulin." (PMID 39575003, 2024). "We observed that MSC-derived sEVs, specifically those from WJ-MSCs overexpressing apelin, effectively enhance insulin sensitivity, increase glucose uptake in peripheral tissues, and inhibit hyperglycemia and β-cell apoptosis." (PMID 38622732, 2024). "Insulin exposure increases the proliferation of mouse beta-cells, and blocking insulin secretion with somatostatin blunts the proliferation induced by hyperglycemia." (PMID 39120275, 2024). "Second, patients with acute infection tend to develop hyperglycemia and increased insulin secretion." (PMID 38590318, 2024). "Exenatide significantly reduced glucose excursions during a 300 min period compared to insulin alone, implying a significant reduction in postprandial hyperglycemia." (PMID 39273299, 2024). "Gestational diabetes mellitus (GDM), a state of hyperglycemia due to insufficient insulin secretion and/or insulin resistance that occurs during pregnancy, is the most common metabolic disorder of pregnancy, affecting 6–12% of pregnancies globally." (PMID 38216688, 2024). "The same up-regulation of Slc2a1 was seen in the hearts of FH mice, supporting insulin resistance, and increased unregulated glucose uptake in the face of permanent hyperglycaemia in the remodelled myocardium of Foz mice with MASH." (PMID 39206703, 2024). "Before launching SGLT2-I, first-line drugs for treating hyperglycemia have been insulin secretagogues, insulin sensitizers, gluconeogenesis inhibitors, and glucose absorption inhibitors, either alone or in combination." (PMID 38304078, 2024). "This interferes with both insulin signaling and transmembrane glucose uptake, which induces plasma hyperglycemia and glucotoxicity." (PMID 39063184, 2024). "Of the 12 patients who had new or increased hyperglycemia on daily blood glucose measurements, nine had minor adjustments to their non-insulin diabetic medication management, two required initiation of insulin, and one had an increase in insulin requirements." (PMID 38765324, 2024). "Early identification and appropriate treatment of hyperglycemia in prediabetics is important, as impairments in pancreatic beta-cell functioning and resistance to insulin are already present before the onset of T2DM." (PMID 39022458, 2024). "In this cohort study, home insulin pump use was found to be safe in a children’s hospital regarding hyperglycemia and hypoglycemia." (PMID 38324312, 2024). "This, in turn, hinders the insulin response and glucose absorption in muscles and adipose tissues, promoting hyperglycemia." (PMID 39206042, 2024). "Patients with IR-related features also had earlier onset of T1D, reported higher daily insulin dose, exhibited higher hyperglycemia exposure, had a higher prevalence of DK/DKA and diabetic complications, and experienced more hypoglycemia episodes." (PMID 38212850, 2024). "By inhibiting DPP-4, these drugs increase the levels of GLP-1 and GIP, which in turn increase insulin secretion by pancreatic beta-cells, therefore reducing postprandial and fasting hyperglycemia." (PMID 39336583, 2024). "The patient experienced gradual refractory intraoperative hyperglycemia, peaking in the neo-hepatic phase, requiring frequent insulin boluses, and a progressive increase in the basal rate up to 24 units/hour at the end of surgery." (PMID 39347258, 2024). "Once the STZ-treated mice developed hyperglycemia (BG > 300 mg/dl), insulin pellets were implanted subcutaneously as a bridge to maintain a reasonable BG in these mice." (PMID 38702347, 2024).
Hyperglycemia (continued). "One of the first studies to use STZ generated a drug‐induced zebrafish model of T1DM that resulted in sustained hyperglycaemia with reduced insulin secretion by the endocrine pancreas and early signs of retinopathy and nephropathy." (PMID 38279951, 2024). "Among the traits related to hyperglycemia, ALT is a risk factor for fasting glucose and fasting insulin; on the other hand, HbA1c and two-hour post challenge glucose cannot be affected by ALT." (PMID 38662679, 2024). "The coefficient of 1.6 mmol/L per 5.6 mmol/L is supported by findings in severe hyperglycemic episodes treated by insulin infusion in oligoanuric patients, in studies of treatment of hyperglycemia in patients with preserved renal function, and in dogs as well." (PMID 39797108, 2024). "Recent studies using CGM (or flash glucose monitoring, FGM) during RF have confirmed an increased time in hyperglycemia and glucose variability, especially in subjects with type 1 diabetes receiving insulin therapy." (PMID 39203800, 2024). "Patients experience both aberrantly elevated glucagon levels (hyperglucagonemia), further exacerbating their hyperglycemia, and impaired alpha cell response to iatrogenic hypoglycemia secondary to insulin therapy." (PMID 39594662, 2024). "We demonstrate that the HFD + STZ model is more consistent in the in vivo development of hyperglycemia and exhibits concomitant insulin resistance, in comparison to the STZ model." (PMID 38673735, 2024). "Key adipokines such as leptin, resistin, and ghrelin disrupt insulin signaling, inhibit glucose receptor activity, and contribute to hyperglycemia." (PMID 39596980, 2024). "In contrast, hyperglycaemia requiring intermittent insulin only occurred in patients treated with Cy/ATG, likely due to the high doses of methylprednisolone used in this protocol." (PMID 39187603, 2024). "As a result, hyperglycemia develops, which is characteristic of DM, and which leads to insulin overproduction by the β-cells to the point of failure." (PMID 39123454, 2024). "All these measurements return to near-normal values within 24 h following correction of hyperglycaemia with insulin therapy and hydration." (PMID 38907161, 2024). "OL provoked an increase in circulating insulin which partially seems to contribute to the attenuation of hyperglycemia, in line with several approved antidiabetic pharmacological agents." (PMID 39153251, 2024). "Improved insulin sensitivity in the liver contributes to restoring normal hepatic glucose production during fasting, reducing the toxic effect of hyperglycemia on β-cells." (PMID 38942960, 2024). "Hybrid closed-loop systems (HCLSs) aid in the management of hyperglycemia and the reduction in hypoglycemia by automatically adjusting insulin infusion based on real-time continuous glucose sensor readings and predictive algorithms." (PMID 39064653, 2024). "It is well-established that T2DM patients are characterized with hyperglycemia resulting from insufficient insulin sensitivity and defective insulin secretion." (PMID 39580381, 2024). "It is also believed to have direct anti-inflammatory effects by inhibiting nuclear factor κB (NF-κB) activation and reducing the release of inflammatory cytokines like interleukin-6 (IL-6), as well as indirectly by lowering hyperglycemia and insulin levels." (PMID 39459443, 2024). "Further experiments proved that this severe HTG was insulin dependent and was similar to the development of hyperglycemia because the plasma TG quickly returned to almost normal levels after insulin injection." (PMID 39529532, 2024). "Ketone bodies, typically produced during states of a decreased glucose level or insulin availability, are now synthesized in response to hyperglycemia, indicating the robust metabolic adaptability of astrocytes to varying glucose levels." (PMID 39200266, 2024).
Hyperglycemia (continued). "Stress-induced hyperglycemia can be brought on by a rise in catecholamine, glucagon, growth hormone, pro-inflammatory cytokines, and peripheral insulin resistance in response to physiological stress." (PMID 39727640, 2024). "Although Gpr84‐deficient mice were lean and had increased endogenous MCFAs under high‐fat diet feeding conditions, they exhibited hyperglycemia and hyperlipidemia along with lower plasma insulin and glucagon‐like peptide‐1 levels compared with wild‐type mice." (PMID 39512839, 2024). "This inflammatory and stressful environment interferes with the insulin signaling cascade, resulting in an attenuated response of target tissues to insulin and, consequently, the maintenance of hyperglycemia and hyperinsulinemia." (PMID 39458995, 2024). "Theseantioxidant chemicals found in C. nutans leaf extract have beenshown to repair pancreatic islets in streptozotocin-induced hyperglycemia mice,enhancing insulin output (Vessal etal., 2003)." (PMID 38712836, 2024). "As shown in the in vivo mice measurements, the IWCS system realized the simultaneous glucose monitoring and the treatment of hyperglycemia by insulin administration." (PMID 38225744, 2024). "In contrast, insufficient insulin production results in increased blood glucose levels, leading to hyperglycemia." (PMID 38542818, 2024). "SGLT2 inhibitors are expected to improve hyperglycemia even in the presence of insulin deficiency, while DPP4 inhibitors are effective in those with some preservation of insulin secretion." (PMID 38331780, 2024). "When the body cannot produce or use insulin effectively, that leads to high blood glucose levels (hyperglycemia)." (PMID 38256196, 2024). "It is already known from the literature that zebrafish show a significant response to the increase in insulin under conditions of hyperglycemia." (PMID 39408365, 2024). "Hyperglycemia and insulin resistance impair insulin signaling in the brain, leading to reduced neuronal glucose uptake and energy deficits." (PMID 39728750, 2024). "Any malfunction or improper expression of genes responsible for these channels can lead to a reduction in insulin secretion, ultimately resulting in the development of hyperglycemia." (PMID 39273144, 2024). "The commencement of inavolisib, a small molecule designed to selectively inhibit mutant PIK3CA, immediately resulted in grade 3 hyperglycemia that persisted despite the commencement of metformin and insulin glargine." (PMID 39437820, 2024). "Hyperglycemia, a dangerous status resulting from insulin underdosing, can lead to multiple organ damage and complications." (PMID 39457586, 2024). "Faulty LD dynamics result in lipid accumulation in β-cells, further impairing insulin secretion and contributing to hyperglycemia." (PMID 38999988, 2024). "- High blood glucose levels (hyperglycemia) dueto insufficient insulin production relative to insulinresistance." (PMID 39355538, 2024). "The mechanisms of muscle strength decrease due to hyperglycemia are multifactorial, including insulin resistance, increased secretion of inflammatory cytokines, and oxidative stress." (PMID 39518586, 2024). "Subcutaneous insulin therapy stands today as the the only treatment for T1D, and it requires knowledge of the exact insulin dose to prevent both hypoglycemia and hyperglycemia." (PMID 39024327, 2024). "The continuous traits were divided into hyperglycemia-related traits (fasting glucose, fasting insulin, two-hour post challenge glucose and HbA1c), obesity-related traits (waist-to-hip ratio and BMI) and serum lipids (HDL-C, LDL-C and triglycerides)." (PMID 38662679, 2024). "Although long-term GCGR is linked to hyperglycemia and glucose intolerance (and thus antagonistic to insulin signaling), acute GCGR potentiates glucose metabolism and insulin sensitivity by a mechanism that involves hepatic rictor/mTORC2 and Akt signaling." (PMID 38270460, 2024).
Hyperglycemia (continued). "Hyperglycemia can occur due to increased levels of stress hormones such as steroids, catecholamines, glucagon, and decreased insulin levels due to stress." (PMID 38622332, 2024). "Studies have shown that hyperglycemia is the main component of the metabolic syndrome related to sarcopenia, demonstrating the important relationship between mass and peripheral insulin sensitivity." (PMID 37255103, 2023). "The reduction of β-cell insulin production or defective responses to insulin in tissues are common characteristics of DM disorders and result in high blood glucose levels, termed hyperglycemia." (PMID 36677212, 2023). "According to the authors, the obtained insulin-Gox-loaded PVs demonstrated fast insulin release (90%) under the hyperglycemia conditions (400 mg·dL−1), as well as at pH levels of 5.0 (60%), which confirms their dual-stimuliresponse." (PMID 36982244, 2023). "Feeding a HFD results in IR, and STZ decreases insulin release by damaging β-cells, leading to hyperglycemia." (PMID 37397470, 2023). "Conversely, the Society for Maternal-Fetal Medicine (SMFM) in the United States recommends metformin as the first-line alternative to insulin in women with GDM when diet alone is insufficient in controlling hyperglycemia." (PMID 38063570, 2023). "These substances, stimulated by relatively insufficient insulin secretion or hyperglycemia, were prone to fatty acid oxidation, and in cases of liver and kidney dysfunction, they are more prone to ketoacidosis." (PMID 38111708, 2023). "It was demonstrated that baicalin was effective in suppressing hyperglycemia and improving insulin action." (PMID 38203600, 2023). "This procedure will impair insulin signaling and reduce glucose uptake in peripheral tissues, resulting in hyperglycemia in GDM women." (PMID 37512897, 2023). "It seems that adiposity and hyperglycemia alone or in combination are critical factors in the increase of the levels of insulin, insulin resistance, and acute inflammatory biomarkers." (PMID 37208686, 2023). "Overall, adequate insulin action prevents fasting hyperglycaemia and limits the mealtime glucose excursion in normoglycaemic individuals." (PMID 37132569, 2023). "Regular cardiorespiratory exercise increases insulin sensitivity, reduces time of hyperglycemia, and results in a reduction in glycosylated hemoglobin (HbA1c) by between 0.3% and 0.6%." (PMID 37836433, 2023). "Premix/coformulation insulin can be used in patients having both fasting and postprandial hyperglycemia together and also to reduce the number of injections at the time of intensification." (PMID 36650625, 2023). "Although he was asymptomatic and did not require steroids for the treatment of COVID-19, he was noted to have persistent severe hyperglycemia requiring unusually high levels of intravenous insulin." (PMID 37456416, 2023). "T1D is characterized by pancreatic β-cell destruction leading to hyperglycemia and lifelong insulin reliance." (PMID 37767101, 2023). "Improved glycemic control currently relies on hybrid closed‐loop insulin delivery systems that combine a continuous glucose monitoring device connected to an insulin pump delivering insulin at high glucose levels (hyperglycemia)." (PMID 37718654, 2023). "In clinical translation, increasing FPG within the normal range in subjects with normal glucose tolerance or IGT correlates with decline in hyperglycemia-induced insulin secretion." (PMID 38292764, 2023). "In contrast, we showed here that POSH control can provide on-demand secretion of insulin to normalize hyperglycemia in T1D mice." (PMID 36268868, 2023). "Continuous hyperglycemia in pregnant women can affect the fetal insulin levels, thereby accelerating fetal weight gain." (PMID 36986107, 2023). "As an endogenous preventive mechanism, the β-cell responds to hyperglycemia with a compensatory increase in insulin secretion and cell mass expansion." (PMID 36875493, 2023).
Hyperglycemia (continued). "Whereas a single-center RCT in critically ill children receiving early PN has found improved morbidity and mortality by treating hyperglycemia with insulin, subsequent multicenter RCTs have been neutral." (PMID 37365667, 2023). "Maternal hyperglycemia stimulates the secretion of insulin in large quantities, resulting in faster fetal growth and the formation of macrosomia." (PMID 36910494, 2023). "This phenomenon is described by several authors as the silent degradation of insulin effectiveness, referred to as the prediabetes state or intermediate hyperglycemia." (PMID 37372830, 2023). "IRF8 is an important regulatory gene for the development of dendritic cells, which play a crucial role in the regulation of insulin secretion and hyperglycemia." (PMID 37113991, 2023). "Several preclinical models have emerged to study GDM, including models of diet-induced maternal hyperglycemia, and models of hypoinsulinemia produced by agents that deplete the pancreas of insulin secreting ß-cells, using alloxan or streptozotocin (STZ)." (PMID 37396180, 2023). "He reported intermittent hyperglycemia to 250 mg/dL in the post‐prandial period, and his insulin regimen had been adjusted accordingly at home." (PMID 37255617, 2023). "While insulin has not been studied as a mediator of autophagy or mitophagy in the corneal epithelium in the setting of hyperglycemia, insulin has been shown to inhibit mitophagy in corneal epithelial cells." (PMID 37153108, 2023). "When fed a high-fat diet, transgenic mice with hepatic RELMβ over-expression exhibits obvious hyperglycemia, hyperlipidemia, fatty liver, pancreatic islet enlargement, and hepatic insulin resistance." (PMID 36691020, 2023). "According to the CTCAE v5.016, we noted grade 3 toxicity of hyperglycemia requiring insulin treatment in one patient and grade 2 toxicity in 4 patients." (PMID 37380669, 2023). "In contrast to typical DKA, in which ketoacidosis is preceded by hyperglycemia mainly due to insulin omission or other precipitating factors." (PMID 37400799, 2023). "Another important factor is performance bias, in which patients with DM receive more attention from the medical team in terms of glycemic control to avoid hyperglycemia or hypoglycemia during insulin treatment." (PMID 37697407, 2023). "A study in mice showed that Holdemanella biformis ameliorates hyperglycemia, improves oral glucose tolerance, and restores gluconeogenesis and insulin signaling in the livers of obese mice." (PMID 37371960, 2023). "After receiving insulin therapy, the patient’s hyperglycemia was controlled, but the patient became dependent on insulin therapy from then on due to T1DM." (PMID 38022276, 2023). "In a clinical trial, the addition of 15 mL SI oil to a high-fat breakfast attenuated postprandial hyperglycemia and improved insulin sensitivity in healthy individuals with higher baseline triglycerides and glycemic response." (PMID 38004453, 2023). "In the subset of patients receiving insulin, the median number of hyperglycaemias in patients who were receiving SC insulin of any type was significantly higher than in patients who were not (2 vs 0; median difference: 2 [95%CI 2; 2]; P < 0.0001)." (PMID 37330419, 2023). "In agreement, insulin-mediated correction of hyperglycaemia in IAV-infected, STZ-treated mice reversed the altered total lung DC composition, cDC1 Ki-67+ cells and IL-12 expression." (PMID 38093014, 2023). "Stress hyperglycemia refers to hyperglycemia that commonly accompanies acute andcritical illness; it results from increased insulin resistance and glucoseproduction as part of the pronounced endocrine and metabolic response to acuteillness." (PMID 38265316, 2023). "The insulin expression pattern in the islets of the OA group was similar to the hyperglycemia group, except few insulin positive cells in acinar cells outside of islets." (PMID 37520251, 2023).